CRP (C-reactive protein)
Diseases named in the same sentence as CRP in open-access papers (continued):
Sharing a sentence is not in itself a finding about the gene and the disease.
leukocytosis (continued). "On POD 15, the patient was febrile and laboratory examinations revealed leukocytosis (10,500/μl; normal range, 4000 to 9000/μl) and an increased serum concentration of C-reactive protein (CRP) (9.5 mg/dl; normal range, 0 to 0.3 mg/dl)." (PMID 27921278, 2016). "After the admission to the emergency room, all of them showed low blood pressure, fever >38.5 °C, leukocytosis, and elevated blood levels of CRP." (PMID 26861356, 2016). "On admission, the patient was in septic shock with leukocytosis and elevation of C-reactive protein." (PMID 27906036, 2016). "Prevalence of leukocytosis and positive CRP in the patients reported here is similar to that (57 and 71 %, respectively) in MERS by other causes." (PMID 27836006, 2016). "Of the 17 patients with renal abscesses, all presented with leukocytosis and elevated CRP level (normal range ≥8 mg/L)." (PMID 27876028, 2016). "In our study, all 17 patients had leukocytosis with elevated CRP levels, and 64.7% of them presented with WBC counts >15,000/μL." (PMID 27876028, 2016). "A majority of the patients displayed thrombocytopenia, acute renal impairment (elevated creatinine), systemic inflammation (elevated C-reactive protein and leukocytosis), and increased LDH indicating cell damage." (PMID 26873376, 2016). "Initial laboratory studies revealed leukocytosis and neutrophilia (15 × 103/μl; 90%), a CRP concentration of 15.80 mg/dl (normal value <0.5 mg/dl), and an ESR of 54 mm/h (normal value <20 mm/h)." (PMID 28003031, 2016). "Laboratory studies showed leukocytosis (14,200/μL) with 88.0% of neutrophil, increased levels of serum inflammatory markers such as C-reactive protein (CRP) (12.4 mg/dL), and erythrocyte sedimentation rate (ESR) (50 mm/h)." (PMID 27034879, 2016). "Leukocytosis, positive C-reactive protein, hyponatremia, CSF pleocytosis and slow wave on electroencephalography frequently occurred." (PMID 27836006, 2016). "In univariate analysis, death was associated with a higher Charlson’s comorbidity index, receipt of anticancer chemotherapy and infection by the R017 strain, and with leukocytosis, hypoalbuminemia, azotemia and a higher CRP level." (PMID 28002482, 2016). "Laboratory tests showed mild leukocytosis (11,700/mm3), mild anemia (11.9 g/dL), increased C-reactive protein (CRP) level (37.6 mg/dL), and mild hypoalbuminemia (37.3 g/L)." (PMID 27015206, 2016). "The most common finding at presentation was anemia in 49/82 patients (59.75%), followed by elevated ESR in 45/82 patients (54.87%) and then elevated CRP and leukocytosis in 33/82 patients (40.24%), while thrombocytosis was found in 31/82 patients (37.8%)." (PMID 26966610, 2016). "A 35-year-old male with complaints of high fever and malaise for 3 days visited a nearby clinic, where antibiotic therapy (ceftriaxone 1 g/day) was started based on leukocytosis (10,000/μl) and elevated serum C-reactive protein (CRP) level (7.39 mg/dl)." (PMID 26587361, 2015). "Two weeks after the admission, leukocytosis and serum levels of CRP and LDH were reduced to a normal range." (PMID 26587361, 2015). "ProADM >0.16 nmo/L, with a specificity of 70 % for bacteremia, was as accurate as band neutrophils, or CRP and better than leukocytosis to rule it in." (PMID 26286191, 2015). "Laboratory data showed leukocytosis, with a leukocyte count of 17,500/mm3, and an elevated serum C-reactive protein (CRP) concentration of 13.2 mg/dl." (PMID 26366343, 2015). "Transabdominal and suprapubic ultrasonographic survey, serum quantitative measures for leukocytosis and C-reactive protein (CRP) were conducted at every visit." (PMID 26542676, 2015). "In our daily clinical practice we used only L-lactate, leukocytosis and C-reactive protein as parameters for AMI." (PMID 26413147, 2015). "Blood examination showed leukocytosis (17.33 × 109/L), anemia (11 g/dL), elevated alkaline phosphatases (669 U/L), gamma-glutamyl transferases (117 U/L) and C-reactive protein (77 mg/dL)." (PMID 26474454, 2015).
leukocytosis (continued). "A fever and abnormal laboratory values including leukocytosis with greater than 70% neutrophils, elevated erythrocyte sedimentation rate, and elevated C-reactive protein commonly accompany the cutaneous findings." (PMID 26770858, 2015). "Leukocytosis with increased levels of C-reactive protein of the plasma and elevated erythrocyte sedimentation rate are nearly always present, while fever is a less constant sign." (PMID 26163136, 2015). "In the present study, all patients had elevated PCT and CRP levels, 83 % had either leukopenia or leukocytosis, indicating the induction of systemic inflammation in the course of septic shock." (PMID 26093653, 2015). "Laboratory evaluation was remarkable for leukocytosis 18,000/mm3 (4500–10,000/mm3), and highly elevated C-reactive protein (CRP) levels of 372 mg/dL (normal range < 5 mg/dL)." (PMID 25861277, 2015). "Laboratory investigations revealed leukocytosis of 20,600 cells/μl, an elevated C-reactive protein (CRP) level of 28.6 mg/dl, and a procalcitonin level of 278.99 ng/ml (reference range: ≤0.03 ng/ml)." (PMID 25885337, 2015). "Altogether, a total of 45 out of 54 patients (83.3 %) had leukocytosis (>10 000 /μl), 48 out of 52 patients (92.3 %) had an increase of C-reactive protein (>0.5 mg/dl) and 18 out of 26 patients (69.2 %) had an increase of L-lactate (>1.6 mmol/l)." (PMID 26413147, 2015). "The main risk factors associated with complicated appendicitis are clinical (i.e. male sex, age ≥60 years of age and onset of symptoms) and laboratorial (i.e. leukocytosis, elevated C-reactive protein and bilirubin)." (PMID 26526329, 2015). "Initial leukocytosis and an elevated CRP level made it difficult to distinguish this from a bacterial infection." (PMID 25997046, 2015). "Maternal inflammation or infection, defined as clinical signs of infection and increased CRP or leukocytosis, was likely present in the majority of early occurring episodes." (PMID 25894336, 2015). "Laboratory studies generally reveal evidence of acute inflammation such as leukocytosis and elevated serum CRP." (PMID 26090317, 2015). "Blood examination disclosed a marked leukocytosis (neutrophilia) and elevated serum concentrations of C-reactive protein (CRP) and liver enzymes." (PMID 25123545, 2014). "Leukocytosis (leukocyte count ≥15000/μL) and higher C-reactive protein (>40 mg/L) were both more frequently seen in children with CA4 infection (34% and 40.6%, respectively)." (PMID 24504149, 2014). "Laboratory findings included leukocytosis (64%), leucopenia (27%), thrombocytopenia (50%), an immature/mature neutrophils ratio of >0.25 (47%), and increased CRP (77%)." (PMID 25389439, 2014). "We were also able to compare various factors affecting POF and indicators of infection such as decreased hematocrit (Ht), transfusion, leukocytosis, and an elevated serum C-reactive protein (CRP) level over a longer time period than in previous studies." (PMID 24522863, 2014). "Laboratory testswere within the normal range except for leukocytosis (12.500/mm3) and elevated C-reactive protein (8 mg/L) (CRP)." (PMID 25379164, 2014). "Because laboratory tests showed leukocytosis (15.06 × 109/L), elevated serum C-reactive protein (CRP, 75 mg/L), and low white blood cell (WBC) count in the urine (5–9/HPF), she was diagnosed with a simple renal cyst infection." (PMID 25525537, 2014). "With regard to laboratory findings of pyelonephritis, leukocytosis, neutrophilia and elevated CRP level are common in the acute phase of pyelonephritis." (PMID 25488491, 2014). "In many IRAK-4-deficient patients clinical and laboratory signs of inflammation (such as CRP, IL-6, leukocytosis) develop slowly even in instances of severe infection, as seen in the first sibling in our study." (PMID 24625087, 2014). "Laboratory data revealed leukocytosis (>10,000/uL) with mainly segmented cells in 14 patients (66.7%), and elevated CRP levels and ESR in all 21 patients." (PMID 24755138, 2014).
leukocytosis (continued). "It is known that patients with bacterial or parasitic diarrhea have higher inflammatory signs (higher CRP levels, leukocytosis etc)." (PMID 25793071, 2014). "Consistent with this theory, we found that individuals with leukocytosis and elevated CRP were more likely to demonstrate emphysema and bronchiolitis." (PMID 25354261, 2014). "Positive correlations have been recorded between IL-6 serum levels and clinical severity of PP, as well as associated leukocytosis, ESR, and CRP levels." (PMID 25126586, 2014). "Laboratory and histological findings, although nonspecific, were in line with those of erythroderma, such as mild anemia, leukocytosis with eosinophilia, high levels of CRP, and hypoalbuminemia." (PMID 25295062, 2014). "Laboratory tests showed a decreased leukocytosis (neutrophils 7.74 × 103/μL) but CRP was increased (8.4 mg/dL)." (PMID 25431726, 2014). "Laboratory investigations showed mild leukocytosis, slight elevation of C-reactive protein (CRP) (192 mg/L), and discrete anemia (hemoglobin 10 g/dL)." (PMID 24987535, 2014). "In the patients with severe abdominal pain, significant leukocytosis with neutrophilia along with increased levels of hematocrit were observed while levels of C-reactive protein (CRP) remained low." (PMID 23915279, 2013). "It is irrefutable, however, that leukocytosis and changes in C-reactive protein levels (CRP) correlate strongly with clinical outcomes after-injury." (PMID 24058736, 2013). "Laboratory tests revealed persistent mild leukocytosis and elevated CRP levels (white blood cells 7.500–8.000/μl, CRP 103 mg/l, D-dimer 1,720 mg/ml)." (PMID 22972586, 2013). "In this study, laboratory data showed elevated CRP levels in nine (60%) patients and leukocytosis in three (20%)." (PMID 24148903, 2013). "Usual laboratory findings are leukocytosis, thrombocytopenia, anemia, elevation of plasma C-reactive protein (CRP) and creatinine levels, as well as proteinuria and hematuria." (PMID 23990945, 2013). "Compared with gastric anisakiasis, more patients with small-intestinal anisakiasis exhibited leukocytosis (76.7%), eosinophilia (43.3%), and elevated C-reactive protein levels (3.4 ± 3.2 mg/dL)." (PMID 24455340, 2013). "In the presented case, it is also worth noting that the level of CRP was high while leukocytosis was relatively low." (PMID 22972586, 2013). "Other studies found that subjects with severe periodontitis had increased serum levels of CRP and interleukins, hyperfibrinogenemia, and moderate leukocytosis." (PMID 24386401, 2013). "Blood tests for inflammation were positive, showing elevated C-reactive protein (CRP; 63.9 mg/L vs. normal range: 0-8 mg/L), leukocytosis (25.4 × 109/L vs. 4-10 × 109/L), and elevated neutrophils (21.3 × 109/L vs. 2.0-8.0 × 109/L)." (PMID 24345089, 2013). "Anemia, leukocytosis, high erythrocyte sedimentation rate, C-reactive protein, hypoalbuminemia, elevated total bilirubin, and alanine aminotransferase are the common features." (PMID 24194749, 2013). "Laboratory test showed leukocytosis, neutrophilia, anemia (hemoglobin: 10.9 g/dL), normal platelets count and progressive increase of CRP up to 19.43 mg/dL, ESR of 76 mm/one hour, and serum ferritin levels of 2276 ng/mL (normal up to 300 ng/mL)." (PMID 24303223, 2013). "Our results show, moreover, that leukocytosis, CRP and lactate are good markers of infection to young patients, but not to the aged one." (PMID 23742671, 2013). "Most patients in both groups presented with leukocytosis with left shift, along with a increased C reactive protein level." (PMID 23537455, 2013). "Immunological workup confirmed marked leukocytosis with neutrophilia and anemia, elevated serum C-reactive protein (CRP = 165 mg/L), and fibrinogen (6 g/L)." (PMID 25374740, 2013).
leukocytosis (continued). "While these syndromes display certain distinct characteristics, they also share a number of overlapping symptoms involving recurrent fever, rashes and joint pain, as well as leukocytosis and elevated C-reactive protein (CRP)." (PMID 24098386, 2013). "In the context of a usual bacterial infection, leukocytosis is recognized prior to an increase of CRP." (PMID 23915279, 2013). "Despite two patients (out of palliative care group 3) in all patients a highly significant decrease of initially elevated CRP levels was observed beside normalization of leukocyte blood count in cases of initial leukocytosis." (PMID 23762145, 2013). "The initial tests showed leukocytosis with neutrophilia, high CRP levels, and a positive serum agglutination test for Salmonella Typhi." (PMID 24303223, 2013). "Temperature was elevated (38.8°C) while additional laboratory findings revealed leukocytosis (22.000/mm3) and elevated C-reactive protein (13,5 mg/dL)." (PMID 23024878, 2012). "Other clinical and laboratory findings such as leukocytosis, elevated CRP, diarrhea, cough, rhinorrhea, and perianal desquamation are also suggestive of the diagnosis." (PMID 22454602, 2012). "PUUV nephropathia epidemica is often characterized by a moderate leukocytosis, thrombocytopenia, elevated C-reactive protein (CRP) levels, and a mild transaminitis." (PMID 22523590, 2012). "Typical laboratory findings during the acute phase are leukocytosis, thrombocytopenia, anemia, and elevation of plasma C-reactive protein (CRP) and creatinine levels." (PMID 22347483, 2012). "Her repeat blood count revealed leukocytosis (18,500/mm3) with left shift (90% poly) and elevated C-reactive protein (CRP) of 11.1 mg/dL." (PMID 23304583, 2012). "Blood analysis showed a leukocytosis (18,000/mm3) and elevated c-reactive protein levels (148 mg/L)." (PMID 23346448, 2012). "Upon admission blood tests showed high c-reactive protein (145 mg/L) and moderate leukocytosis (15000/μL)." (PMID 22420484, 2012). "The findings of the present study indicate that in solid-malignancy patients who develop leukocytosis, elevated CRP, and fever, it is important to make an early differential diagnosis between inflammatory disease and G-CSF-producing tumors." (PMID 22713692, 2012). "Under this regime the clinical condition of the patient improved while the leukocytosis and c-reactive protein were declining." (PMID 22420484, 2012). "Abnormal laboratory findings included leukocytosis (14.000/mm3), anemia (Hb: 9 g/dL), and minimally elevated C-reactive protein (2.32 mg/dL)." (PMID 23024878, 2012). "Blood analysis revealed a leukocytosis (20,500/mm3) and an elevated c-reactive protein level (158 mg/L)." (PMID 23346448, 2012). "Leukocytosis with the predominance of polymorphonuclear leukocytes accompanies acute appendicitis in most cases, along with elevated C-reactive protein." (PMID 21481248, 2011). "During the acute phase, an increase in the serum creatinine concentration, thrombocytopenia, anemia, leukocytosis, as well as moderately elevated erythrocyte sedimentation rate and C-reactive protein (CRP) values are typical laboratory findings." (PMID 20500875, 2010). "Blood investigations showed mild anemia with leukocytosis, predominantly eosinophilia and high erythrocyte sedimentation rate and C-reactive protein." (PMID 22043264, 2010). "The obviously reported positive association between cancer and inflammation suggests a potential role for CRP and leukocytosis as possible indicators of cancer development." (PMID 19341447, 2009). "Regarding general inflammatory parameters elevated erythrocyte sedimentation was found in 2% of 66 patients with chronic urticaria, abnormal C-reactive protein in 16% of 88 patients, and leukocytosis in 23% of 133 patients." (PMID 20066173, 2009). "Our patient had a leukocytosis of 20,000/mm3 with a left shift and elevated C – reactive protein (17.5 mg/dl)." (PMID 19660120, 2009).
leukocytosis (continued). "Induction of solid tumor in mice was accompanied by marked cellular, molecular, and biochemical changes that included leukocytosis, elevation of serum c-reactive protein (CRP), and enhanced lipid peroxidation." (PMID 19341447, 2009). "Further, treatment with CP and DHA showed a significant reduction in the tumor size that was paralleled with a fall in both CRP level and leukocytosis." (PMID 19341447, 2009). "With regard to general inflammatory parameters leukocytosis was found in 36/57 children (63%) with acute urticaria and elevated C-reactive protein in 16/36 (44%)." (PMID 20066173, 2009). "Blood tests revealed leukocytosis of 22.3 × 109 cells/L and a high C-reactive protein (CRP) of 421 mg/L." (PMID 19055812, 2008). "Leukocytosis and an elevated C-reactive protein level further emphasized the inflammatory nature of this condition." (PMID 16859530, 2006). "In the current study, inflammatory markers, such as leukocytosis and C-reactive protein, remained unchanged in all groups, which supports the findings of Sen and colleagues." (PMID 16859530, 2006). "Laboratory tests showed leukocytosis and elevated C-reactive protein." (PMID 41773117, 2026). "During summer, CSU patients exhibited higher D-dimer and CRP levels, leukocytosis, neutrophilia, and elevated NLR, suggesting a more pronounced systemic inflammatory and pro-coagulant state compared with CIU patients, who showed relatively higher eosinophil counts." (PMID 41598583, 2026). "Laboratory findings showed leukocytosis, elevated C-reactive protein, and impaired renal function." (PMID 41684987, 2026). "Laboratory studies showed mild leukocytosis and markedly elevated C-reactive protein." (PMID 42306369, 2026). "Laboratory tests revealed leukocytosis and increased C-reactive protein." (PMID 41497096, 2026). "Leukocytosis, mild hyponatremia, and elevated C-reactive protein were found on laboratory workup." (PMID 41804392, 2026). "This critical distinction between a sterile systemic inflammatory response syndrome (SIRS) and true infection was supported by marked inflammatory markers, including a C-reactive protein (CRP) of 285 mg/L, a procalcitonin level of 4.5 ng/mL, and a leukocytosis of 18.5 x 109/L with 90% neutrophils." (PMID 41257153, 2025). "Laboratory evaluation showed leukocytosis and markedly elevated C-reactive protein." (PMID 41404206, 2025). "Initial laboratory tests revealed marked leukocytosis and elevated C-reactive protein (CRP) levels." (PMID 41018469, 2025). "In our patient, leukocytosis and an elevated CRP of 56 mg/L were observed." (PMID 41541170, 2025). "Normal CRP and leukocytosis excluded potential significant infection." (PMID 41156134, 2025). "The most common laboratory findings are leukocytosis and elevated C-reactive protein (CRP) levels." (PMID 39906450, 2025). "The presence of a UTI could easily lead to anchoring bias, attributing systemic signs such as fever, leukocytosis, and elevated CRP solely to the UTI." (PMID 41257102, 2025). "Labs showed leukocytosis, elevated CRP, and prerenal acute kidney injury." (PMID 41018982, 2025). "Prompt imaging and referral may be indicated by early clinical signs, such as nonspecific abdominal discomfort, postmenopausal pelvic masses, or an unexplained rise in inflammatory markers (e.g., CRP and leukocytosis)." (PMID 40821138, 2025). "Interestingly, elevated C-reactive protein (CRP) and leukocytosis, indicating a proinflammatory state, were also associated with both cardiovascular endpoints." (PMID 41226753, 2025). "We intended to investigate other inflammatory biomarkers, such as neutrophil count and C-reactive protein levels in patients with leukocytosis: however, most patients only had information for a WBC count from routine blood tests due to the restrictions under the Japanese health insurance system." (PMID 40826737, 2025).